MBL2 (mannose binding lectin 2)
Diseases named in the same sentence as MBL2 in open-access papers (continued):
Sharing a sentence is not in itself a finding about the gene and the disease.
infectious disease (28 papers, 2008 to 2023). A disorder directly resulting from the presence and activity of a microbial, viral, or parasitic agent in humans. "The MBL2 plays an important role in the innate immune system and few polymorphisms in this gene can be responsible for increased susceptibility to some infectious diseases; therefore, MBL2 insufficiency is related to bacterial infection." (PMID 36832361, 2023). "Owing to the effect of MBL2 polymorphisms on susceptibility to infectious diseases, we aim to evaluate the role of these six known SNPs in the MBL2 gene to a C. trachomatis infection." (PMID 36012556, 2022). "MBL is encoded by the MBL2 gene located on chromosome 10q11.2-q21 and plays a major role in infectious diseases, binding to bacteria (S. aureus and P. aeruginosa)." (PMID 34945117, 2021). "Overall, this implicates the necessity to adopt an extensive locus-wide methodology by the future association studies to apprehend the clinical significance of MBL2 polymorphisms in a variety of infectious diseases." (PMID 33681468, 2021). "The mannose binding lectin 2 (MBL2) gene encodes for a calcium-dependent plasma lectin that has been shown to play an important role in innate immune response to various infectious diseases." (PMID 34583337, 2021). "Apart from this, it is necessary to adopt an extensive locus-wide methodology to apprehend the clinical significance of MBL2 polymorphisms in a variety of infectious diseases by the future studies." (PMID 33681468, 2021). "Further, it explains and strengthens the need of more extensive locus-wide approach by future association studies to apprehend the clinical significance of MBL2 polymorphisms, apart from the standard ones, in a variety of infectious diseases." (PMID 33681468, 2021). "The study showed that MBL2 polymorphisms are involved in several infectious diseases and the top ranked rs7096206 has been annotated as deleterious to the protein’s function and described as one of the most functionally important variants in the gene." (PMID 33805090, 2021). "A significant part of the human population has a congenitally low production level and/orlow MBL activity due to the carriage of various MBL2 variants, which can modify the course of a wide range of infectious diseases." (PMID 35088000, 2020). "This will assist in making complete genotype profile of the MBL2 gene for TB susceptibility, and would significantly help in the global control and outcome of this infectious disease." (PMID 27876780, 2016). "Structural and promoter polymorphisms in the MBL2 gene that are responsible for low MBL levels are associated with susceptibility to infectious diseases." (PMID 24595015, 2014). "The deficiency of MBL, caused by the polymorphisms in MBL2 gene, has been associated with susceptibility to various infectious diseases with wide etiology from both virus and bacteria." (PMID 24558451, 2014). "The genetic MBL2 variants have been found to be associated with differences in susceptibility to a variety of infectious diseases and autoimmune disorders." (PMID 21695215, 2011). "The association of MBL2 polymorphisms with infectious diseases has previously been documented." (PMID 32913345, 2020). "It has been reported that single nucleotide polymorphisms located within the promoter region and exon 1 of the MBL2 gene are correlated with mannose-binding lectin serum levels and, consequently, are associated with a higher risk of developing infectious disease." (PMID 27404661, 2016). "Apart from MBL2 polymorphisms, SNPs of toll-like receptor (TLR) family and signaling adaptor proteins have been shown to influence susceptibility to a variety of infectious diseases." (PMID 34583337, 2021). "Mutations in the MBL2 gene can significantly change the serum level of MBL, and consequently alter the susceptibility and progression of infectious disease." (PMID 27824315, 2016).
infectious disease (continued). "Genetic variations in MBL2 that reduce circulating levels and alter functional properties of the mannose binding lectin (MBL) have been associated with many autoimmune and infectious diseases." (PMID 18452612, 2008). "This pilot study is a preliminary research on MBL2 gene and infectious diseases in DRC." (PMID 31941497, 2020). "In addition, 3 substitutions including 2 in the promoter region of MBL2 (-550C/G or rs11003125 and -221G/C or rs7096206) and one in the UTR within the exon 1 (c.4T/C or rs7095891) have been shown to affect the level of MBL protein and influence the outcome of infectious diseases." (PMID 31941497, 2020).
cancer (26 papers, 2010 to 2025). A tumor composed of atypical neoplastic, often pleomorphic cells that invade other tissues. "MBL2 serves as a crucial regulator of the innate immune response and represents a prime candidate for genetic association studies in cancer due to its genomic heterogeneity." (PMID 37835594, 2023). "The difference between LYMPH and C groups with regard to genotype 1 (23.7 vs. 37.2%; p = 0.01) was statistically significant, possibly the first association of a MBL2 gene 3′-untranslated region polymorphism with cancer to be observed in Caucasians." (PMID 30294330, 2018). "To date, several studies have examined the relationship between polymorphisms in the MBL2 gene and cancer risk." (PMID 23637788, 2013). "In these studies, MBL2 polymorphisms resulting in lower serum levels have been associated with higher risk of cancer." (PMID 23637788, 2013). "Some reports have suggested that elevated levels of ECM1 and MBL2 play important roles in cancer development and progression, implying their prospective utility as biomarkers for identifying high‐risk patients and as prognostic tools for clinicians." (PMID 40545963, 2025). "Of these components, MBL2 and FCN3 are some of the mannose-binding lectin pathways’ complement initiators that bind to antigens on the cell membrane of cancer cells or cells, initiating the activation of the complement cascade." (PMID 39796711, 2024). "A correlation analysis showed that MBL2 was significantly negatively corr elated with cancer stem cell-related markers, such as NANOG and SOX9." (PMID 37835594, 2023). "Recognizing the pivotal role of miRNAs in cancer regulation, we substantiated the downregulation of miR-34c-3p targeting MBL2." (PMID 37835594, 2023). "Then, TCGA pan-cancer cohorts were used to explore MBL2 gene expression." (PMID 37835594, 2023). "Our findings revealed a correlation between low MBL2 expression and the activation of various malignant pathways, including the cell cycle, DNA replication, miRNAs in cancer, the vascular endothelial growth factor signaling pathway, and the cancer stem cell-related pathway." (PMID 37835594, 2023). "As a matter of fact complement and coagulation cascade has been reported to be the most perturbed pathway in various cancers strengthening the notion that MBL2 may serve as a good predictive and prognostic clinical biomarker." (PMID 26414287, 2015). "To confirm the impact of altered ECM1, MBL2, BTD and RAB5C expression in existing clinical patient studies, we analysed four biomarker‐altered and non‐altered groups with a survival of 1084 patients in the pan‐cancer atlas and 2509 patients in the METABRIC data." (PMID 40545963, 2025). "Although the underlying mechanism was not clear, but we assume that maintaining high MBL2 level may reduce the inflammatory damage and can inhibit the progression of cancer." (PMID 27557564, 2016).
bacterial infections (12 papers, 2012 to 2025). "Genetic variants in the FCN2 gene double the chance of bacterial infection in the first year following liver transplant, a risk further increased with the coinheritance of MBL2 gene variants." (PMID 28894916, 2018). "Using expression quantitative trait loci (eQTL) analysis, we found that the C7 rs6876739 CC genotypes and mannan-binding lectin (MBL2) gene polymorphisms of liver donors were significantly associated with bacterial infection in recipients." (PMID 27063552, 2016). "Subsequently, we confirmed these results in an extended validation group of 113 patients and found that polymorphisms in two complement component genes, C7 (for MAC formation) and MBL2, were significantly associated with bacterial infection." (PMID 27063552, 2016). "We further investigated whether the identified C7 rs6876739 and MBL2 rs11003125 SNPs were independent risk factors for post-surgical bacterial infection." (PMID 27063552, 2016). "Thus ficolin-2 insufficiencies might play an advantageous role in the protection against Leishmania as do MBL2 polymorphisms for bacterial infections." (PMID 22457818, 2012). "One study investigated the interplay between TGFβ1 and MBL2 in a cohort of 1019 Canadian paediatric CF patients, reporting that high TGFβ1 production enhanced the modulatory effect of MBL2 on the age of first bacterial infection and the rate of decline of lung function." (PMID 33924524, 2021). "MBL2 gene polymorphisms were found to be associated with low levels of serum MBL, indicating that the donor MBL2 rs11003125 genotype is predictive of an increased risk of bacterial infection in recipients after LT." (PMID 27063552, 2016).
cardiovascular disease (10 papers, 2009 to 2020). "On the other hand, others have found that high serum MBL-concentrations and wild type MBL2 may be associated with increased risk of cardiovascular disease." (PMID 22848725, 2012). "Further understanding of MBL2 expression may improve our ability to understand and disrupt the pathogenetic mechanisms involved in cardiovascular disease." (PMID 19161617, 2009). "Thus, MBL2 may contribute to the progression of cardiovascular disease (CVD) among American Indians indirectly through pathogen interactions in addition to its previously defined roles." (PMID 30629683, 2019). "Common variations in the MBL gene (MBL2), between 12 to 25% allele frequencies in Caucasian and other populations, result in markedly lower levels of circulating MBL and are associated with both an increased susceptibility to infections and cardiovascular disease in many, but not all studies." (PMID 19161617, 2009).
heart disease (2 papers, 2016 to 2019). "Previous investigations within the Strong Heart Study cohort identified links between heart disease and low functioning MBL2 genotypes." (PMID 30629683, 2019). "However, a link between MBL2 genotype and Cp in contributing to heart disease has not been established." (PMID 30629683, 2019).
degenerative diseases (1 paper, 2017). "Some studies have reported an association between MBL2 polymorphisms and the clinical manifestations of chronic and degenerative diseases, including a positive association between MBL2 variants and vaso-occlusive crises (VOC) in patients with SCA." (PMID 28837214, 2017).
MBL2 also shares sentences with these, for which no sentence is quoted: pancreatic ductal adenocarcinoma (7 papers); SARS-CoV infection (6); Arthritis (5); bronchiectasis (5); gastric cancer (4); ischemic stroke (4); bacterial vaginosis (3); hepatitis C (3); Hypertension (3); lung disease (3); membranous nephropathy (3); Neonatal sepsis (3); pneumococcal infection (3); primary Sjögren syndrome (3); Respiratory tract infection (3); rheumatic heart disease (3); acute myeloid leukaemia (2); age-related macular degeneration (2); autoimmune thyroid disease (2); benign tumours (2); bronchiolitis obliterans (2); bronchopulmonary dysplasia (2); chronic hepatitis B (2); colitis (2); complement deficiencies (2); cryptococcal infections (2); Cryptococcal meningitis (2); cytomegalovirus infection (2); endometriosis (2); Hepatitis (2).
A further 108 diseases each share a sentence with MBL2 in 2 papers or fewer.